LASP1 (LIM and SH3 protein 1)
Diseases named in the same sentence as LASP1 in open-access papers (continued):
Sharing a sentence is not in itself a finding about the gene and the disease.
cervical cancer (continued). "To confirm if LASP1 plays a role in the development of cervical cancer, we compared cervical cytology samples from a cohort of HPV16+ patients to samples from healthy, HPV- patients." (PMID 38789663, 2024). "Restoration of LASP1 in miR-203 mimic expressing cells completely abolished the proliferation defects observed, demonstrating that LASP1 is a major target of miR-203 in HPV+ cervical cancer cells." (PMID 38789663, 2024). "For example, miR-342-3p can stimulate the malignant potential of NSCLC by regulating the expression of LASP1, and miR-221-3p can promote angiogenesis in cervical cancer by regulating the expression of THBS2." (PMID 35812727, 2022). "Here, we demonstrate that LASP1 functions as a proto-oncogene in HPV+ cervical cancer cells." (PMID 38789663, 2024). "Finally, using the TCGA dataset, we observed that high LASP1 expression significantly correlated with worse overall survival in cervical cancer." (PMID 38789663, 2024). "Here, we demonstrate that miR-203 targets and represses LASP1 in HPV+ cervical cancer cells." (PMID 38789663, 2024). "HPV18+ cervical cancers are associated with a higher chance of metastasis and mortality rates and the ability of HPV18 E7 to drive LASP1 and its effects on the proliferation and invasive phenotype may be a contributing factor." (PMID 38789663, 2024). "Next, we investigated the impact of LASP1 depletion on cervical cancer proliferation." (PMID 38789663, 2024). "To investigate whether LASP1 plays a role in HPV+ cervical cancer, we first utilised the GEO database." (PMID 38789663, 2024). "Finally, we demonstrate that LASP1 expression is required for the growth of HPV positive cervical cancer cells in an in vivo tumourigenicity model." (PMID 38789663, 2024). "Finally, we demonstrated that LASP1 expression is required for the growth of HPV+ cervical cancer cells in an in vivo tumourigenicity model." (PMID 38789663, 2024). "Migration and invasion assay demonstrate that the SH3 domain is required for the pro-invasive functions of LASP1 suggest that these interactions could be important in cervical cancer cells." (PMID 38789663, 2024). "This may be mediated by the loss of LASP1 interacting proteins that are required for production of filopodia-like protrusions; future studies aimed at dissecting the role of each domain in driving these oncogenic phenotypes driven by LASP1 in cervical cancer are warranted." (PMID 38789663, 2024). "Together, these data suggest that LASP1 may function as an oncogene in cervical cancer." (PMID 38789663, 2024). "Our data demonstrate that LASP1 is essential in the migratory and invasive phenotype of HPV+ cervical cancer cells." (PMID 38789663, 2024). "Taken together, these data demonstrate that LASP1 promotes the migratory and invasive phenotype of HPV+ cervical cancer cells in an SH3-dependent manner, but promoted actin dynamics in a manner dependent on both the LIM and SH3 domains." (PMID 38789663, 2024). "The viral oncoprotein E7 upregulates the expression of LASP1, which is a critical driver of proliferation in HPV+ cervical cancer cells." (PMID 38789663, 2024). "LASP1 KD resulted in a significant decrease in both migration and invasion in HPV+ cervical cancer cells." (PMID 38789663, 2024). "Furthermore, a previous study demonstrated that the lncRNA CBR3-AS1 regulated LASP1 in cervical cancer via miR-3163; however, a functional assessment of the role LASP1 plays in cervical cancer was not examined further in this study." (PMID 38789663, 2024). "As our data demonstrated that LASP1 was increased in HPV+ cervical cancer cell lines, but not in an HPV- cervical cancer cell line, we investigated if HPV played an active role in the upregulation of LASP1." (PMID 38789663, 2024). "Interestingly, we did not observe a growth defect in HPV- cervical cancer cells, or those harbouring non-HR HPV30, upon LASP1 depletion; this suggests that LASP1-dependency may be HPV-specific." (PMID 38789663, 2024).
Cirrhosis (2 papers, 2015 to 2017). A chronic disorder of the liver in which liver tissue becomes scarred and is partially replaced by regenerative nodules and fibrotic tissue resulting in loss of liver function. "We investigated the association of LASP-1 and its interactors with clinical parameters, including gender, HBV viral status, ALT, main tumour size, multinodular disease, cirrhosis, BCLC staging and AFP, in HBV-related HCC tissues." (PMID 28266596, 2017). "Therefore, the evaluation of LASP-1 mRNA levels in cirrhotic livers (i.e. in liver biopsies) might be a useful tool to monitor the progression of the disease from hepatic cirrhosis to the HCC stage." (PMID 25760690, 2015).
endometriosis (2 papers, 2022 to 2024). The growth of functional endometrial tissue in anatomic sites outside the uterine body. "Our previous two-dimensional electrophoresis experiment showed that the expression of LASP1 in patients with endometriosis was significantly higher than that of control endometrium." (PMID 35379225, 2022). "Herein, qPCR was performed to analyze the expression levels of LASP1 and miR-218-5p between endometriosis (Ems) cells and control cells." (PMID 35379225, 2022). "The qPCR results showed that ESCs from ectopic endometrium (whether from adenomyosis or endometriosis) appear to be similar in LASP1 and miR expression, suggesting that perhaps these are related diseases merely involving different anatomical sites." (PMID 35379225, 2022). "However, the molecular mechanism by which LASP1 is regulated in endometriosis/adenomyosis is unknown." (PMID 35379225, 2022).
invasive ductal carcinoma (2 papers, 2007 to 2010). "The rate of strongly LASP-1 expressing samples of invasive ductal carcinomas amounted 55.4% (LASP-1-IRS > 5)." (PMID 17956604, 2007). "This study is the first description of LASP-1 as a nuclear protein, whose cytosolic expression and nuclear localization correlates in vivo with tumor size and nodal positivity of human invasive ductal carcinoma of the breast." (PMID 17956604, 2007).
metastatic tumor (2 papers, 2016 to 2018). "In addition, the LASP1 mRNA levels were found inversely correlated with miR-145 levels in the metastatic tumor specimens from the 33 CRC patients." (PMID 27626692, 2016). "As compared to tumors without metastasis, LASP1 expression was stronger in metastatic tumors." (PMID 29531214, 2018).
osteosarcoma (2 papers, 2023 to 2024). A usually aggressive malignant bone-forming mesenchymal neoplasm, predominantly affecting adolescents and young adults. "Based on that, combined with MTX-resistant mRNA and miRNA data, we established a new 4-gene prognostic signature for osteosarcoma, including two high-risk MTXDEGs (CPE, PDK1) and two low-risk MTXDEGs (LASP1, LACTB)." (PMID 37937197, 2023). "After the downregulation of LASP1, the resistance of osteosarcoma cells to cisplatin was reduced, the IC50 decreased, and the knockdown of LASP1 could result in the inhibition of the proliferation of osteosarcoma cells." (PMID 37937197, 2023).
thyroid cancer (2 papers, 2019 to 2024). "Most recently, a study showed that LASP1 was overexpressed in thyroid cancer and contributed to strong cell proliferation and migration ability of thyroid cancer cells through activation of PI3K/AKT pathway." (PMID 31372094, 2019).
atherosclerosis (1 paper, 2022). A disease characterized by the build-up of fatty material and calcium deposition in the arterial wall resulting in partial or complete occlusion of the arterial lumen. "Thus, our study showed that DSY potentially exerted anti-EndMT activity through the LASP1/PI3K/AKT pathway, providing a possible new therapeutic intervention for atherosclerosis." (PMID 36091823, 2022).
benign prostatic hyperplasia (1 paper, 2014). A non-cancerous nodular enlargement of the prostate gland. "By immunohistochemical staining and semi-quantitative image analysis of whole tissue sections we found an enhanced expression of LASP1 in primary PCa and lymph node metastases over benign prostatic hyperplasia." (PMID 24980827, 2014).
cholangiocarcinoma (1 paper, 2022). A carcinoma that arises from the intrahepatic biliary tree (intrahepatic cholangiocarcinoma) or from the junction, or adjacent to the junction, of the right and left hepatic ducts (hilar cholangiocarcinoma). "In intrahepatic cholangiocarcinoma, exosomal miR-206 reduced the expression of LIM and SH3 protein 1 (LASP1) and suppressed the activity of STAT3 signaling to inhibit cholangiocarcinoma stem-like characteristics and TGF-β1 secretion." (PMID 35592419, 2022).
chondrosarcoma (1 paper, 2022). A malignant cartilaginous matrix-producing mesenchymal neoplasm arising from the bone and soft tissue. "Considering LASP1’s established association with malignancy, comparison between chordomas and chondrosarcomas in terms of LASP1 expression might provide further insights into the pathobiological difference between the two." (PMID 35507100, 2022). "Our purpose was to evaluate the expression of LASP1 in primary skull-base chordoma and chondrosarcoma and to gain an understanding of its sub-cellular localization." (PMID 35507100, 2022). "LASP1 is strongly expressed in the majority of chordoma cases and shows low expression in chondrosarcoma tissue." (PMID 35507100, 2022). "Based on a chordomas and chondrosarcomas proteomics iTRAQ (isobaric tags for relative and absolute quantitation) experiment, LIM and SH3 protein 1 (LASP1) was previously suggested to be involved in chordoma pathobiology." (PMID 35507100, 2022). "Evaluation of the TMA used here shows that LASP1 differentiates between the chordomas and the sole chondrosarcoma, and western blot and real-time quantitative PCR results do suggest LASP1’s diagnostic potential as well." (PMID 35507100, 2022). "Chordomas behave more aggressively than chondrosarcomas and a distinct difference in LASP1 expression between the two entities becomes evident from the data presented." (PMID 35507100, 2022). "Though all chondrosarcoma samples also exhibited a LASP1 immunoreactive band at 36 kDa, the expression levels were strongly reduced compared to those in chordoma samples." (PMID 35507100, 2022). "The data presented highlight the expression of LASP1 in chordoma, and its relative lack thereof in chondrosarcoma." (PMID 35507100, 2022). "In contrast, 0/6 chondrosarcoma samples showed detectable levels of LASP1 mRNA and only a weak 36 kDa band was observed in 4/5 cases." (PMID 35507100, 2022). "Biopsies of primary tumors were collected from surgically treated chordoma (n = 6) and chondrosarcoma (n = 6) patients, flash-frozen upon collection and collectively analyzed for LASP1 RNA (real-time PCR) and protein expression (western blotting)." (PMID 35507100, 2022). "In this study we compare LASP1 expression in chordoma and chondrosarcoma tissue." (PMID 35507100, 2022). "However, further immunohistochemical research evaluating a larger number of chondrosarcomas is required to assess the specificity and sensitivity of LASP1 in distinguishing (chondroid) chordomas from chondrosarcomas on immunohistochemistry." (PMID 35507100, 2022). "Four chordoma and none of the chondrosarcoma samples showed detectable LASP1 cDNA levels." (PMID 35507100, 2022).
chordoma (1 paper, 2022). Chordomas are rare malignant tumors arising from embryonic remnants of the notochord in axial skeleton. "Thus, differentiating between the two entities is important and it is interesting to study differentially expressed factors such as LASP1, that might be implicated in the tumor biology of chordoma." (PMID 35507100, 2022). "This study aims to investigate the expression of LASP1 in chordoma, and aims to gain first insight into its cellular localization by virtue of tissue microarray-based immunohistochemistry." (PMID 35507100, 2022). "Results from the gene expression experiment, the western blot data and immunohistochemistry in particular show convincingly, for the first time, that LASP1 is expressed in the majority of chordomas." (PMID 35507100, 2022). "LASP1 was previously identified as a possibly overexpressed protein in a chordoma proteomics experiment." (PMID 35507100, 2022). "Further studies are warranted to improve understanding of LASP1’s expression and functioning within chordoma, both in vitro and in vivo." (PMID 35507100, 2022). "Expression at both mRNA and protein level indicate that LASP1 is prominently expressed in the majority of chordomas, both in cytosolic and nuclear compartments." (PMID 35507100, 2022). "In chordoma samples, LASP1 mRNA was detected in 4/6 cases and a strong 36 kDa immunoreactive protein band was observed in 4/5 cases." (PMID 35507100, 2022). "Since LASP1 is known to function as oncogene and regulate cell proliferation in other tumor types, this study implicates a role for LASP1 in chordoma biology." (PMID 35507100, 2022). "Immunohistochemical evaluation showed a strong immunoreactive LASP1 signal in 23 chordoma specimen." (PMID 35507100, 2022). "Interestingly, the 17q arm on which the LASP1 gene resides, is known to be amplified in in some chordomas, showing gains of chromosomal material in 21% of chordomas." (PMID 35507100, 2022). "The remaining 23 chordoma samples, showed prominent LASP1 positivity in a heterogenic fashion." (PMID 35507100, 2022). "Four chordoma samples also showed a prominent LASP1 immunoreactive band at 36 kDa." (PMID 35507100, 2022). "The mean Ct of the LASP1-positive chordoma samples was 33.1 (range 32.06–34.51)." (PMID 35507100, 2022). "Furthermore, LASP1 has been shown to be involved in mouse vertebral chondrocyte development, which is interesting considering the notochordal fate hypothesis of chordoma." (PMID 35507100, 2022). "In terms of protein localization within primary skull base chordoma cells, the TMA has shown LASP1 to be expressed in both the cytoplasm and the nucleus." (PMID 35507100, 2022). "LASP1 expression has not been actively investigated in chordomas." (PMID 35507100, 2022). "Not all chordomas show LASP1 positivity in the gene expression and western blot assay, thus a degree of heterogeneity (both between tumors, and within different cell populations of the same tumor) may exist to account for this difference." (PMID 35507100, 2022). "Long-term follow up of patients with chordomas showing LASP1 positivity versus those that do not, may offer valuable insights in disease aggressiveness and a possible role of LASP1." (PMID 35507100, 2022). "LASP1 expression has not been demonstrated before in chordoma." (PMID 35507100, 2022).
diabetic nephropathy (1 paper, 2015). "Therefore, LASP1 might serve as prognostic marker for the development of diabetic nephropathy." (PMID 25622104, 2015).
diffuse intrinsic pontine glioma (1 paper, 2015). A neuroglial tumor that arises from the middle portion of the brain stem. "In contrast, expression analysis for ependymoma and diffuse intrinsic pontine glioma (DIPG) exhibited significant LASP1 underexpression (p<0.005 and p<0.05, respectively) as compared to normal brain tissues." (PMID 25622104, 2015).
Ems (1 paper, 2022). "Based on our preliminary data, we found that the expression level of LASP1 protein was significantly increased in ectopic ESCs of Ems patients." (PMID 35379225, 2022). "Based on the expression pattern of LASP1 and miR-218 in different endometrial stromal cells in this study, abnormal gene expression in stromal cells of patients with Ems can be analyzed." (PMID 35379225, 2022). "Our primary data suggested that LASP1 in ectopic endometrial tissue of Ems patients was significantly up-regulated, which strongly suggests that LASP1 protein plays an important role in the development of Ems." (PMID 35379225, 2022). "Therefore, it is speculated that LASP1 affects the migration of ESCs and promotes the pathogenesis of Ems." (PMID 35379225, 2022).
gastrointestinal stromal tumor (1 paper, 2020). "In contrast, RB1 that was regarded as a tumor suppressor gene in gastrointestinal stromal tumors and was identified as a monotonically increasing gene, while three oncogenes including NFE2L2, ABL1, and LASP1 were identified as monotonically decreasing genes." (PMID 33273919, 2020).
hepatic disease (1 paper, 2015). "No clinic parameter (gender, age, tumor grading, TNM, viral hepatitis infection and background hepatic disease) correlated with the LASP-1 mRNA levels in these three subgroups." (PMID 25760690, 2015). "No clinic parameter correlated with the LASP-1 mRNA expression (gender, age, tumor grading, background hepatic disease, viral hepatitis infection) in the 3 groups." (PMID 25760690, 2015).
invasive carcinoma (1 paper, 2007). A carcinoma that is not confined to the epithelium, and has spread to the surrounding stroma. "Strong cytoplasmatic expression of LASP-1 was detected in 55.4 % of the invasive carcinomas, which correlated significantly with nuclear LASP-1-positivity (p = 0.0014), increased tumor size (p = 0.0159) and rate of nodal-positivity (p = 0.0066)." (PMID 17956604, 2007).
laryngeal carcinoma (1 paper, 2021). Carcinoma that arises from the laryngeal epithelium. "Combining previous studies, overexpressed LASP1 could be involved in recurrence of laryngeal cancer." (PMID 34976784, 2021). "Our data confirmed that RCN1, DNAJA2, LASP1 and IBSP were up-regulated while LAT2, FUZ, HOOK2 and DAPK2 were down-regulated in laryngeal cancer." (PMID 34976784, 2021). "RCN1, DNAJA2, LASP1 and IBSP were up-regulated in laryngeal cancer." (PMID 34976784, 2021).
lentivirus infection (1 paper, 2020). Virus diseases caused by the Lentivirus genus. "The mRNA and protein levels of LASP1 were significantly decreased after the lentivirus infection." (PMID 31793711, 2020).
liver fibrosis (1 paper, 2017). "Validated by Western blotting in CCl4-induced liver fibrosis development and regression, the expression of Filamin A and LASP1 protein were found increased as the expression of α- SMA and the expression of NAMPT in liver fibrosis was decreased." (PMID 28322315, 2017).
malignant glioma (1 paper, 2022). A grade III or grade IV glioma arising from the central nervous system. "Malignant glioma cells produce LIM and SH3 protein 1 (LASP1), LIM, and SH3 protein 1, all of which have been demonstrated to enhance cell proliferation and invasion by activating the PI3K/Akt/snail signaling cascade." (PMID 35163279, 2022).
mesothelioma (1 paper, 2022). A usually malignant and aggressive neoplasm of the mesothelium which is often associated with exposure to asbestos. "A Kaplan-Meier survival analysis revealed that high expressions of AUNIP, FANCI, LASP1, PSMD8, and XPO5 were clearly associated with poor OS and RFS, suggesting that the five candidate genes play important roles in the tumorigenesis and progression of mesothelioma." (PMID 35846349, 2022). "AUNIP, FANCI, LASP1, PSMD8, and XPO5 are putative antigens for the development of anti-mesothelioma mRNA vaccine and patients with the IS1 subtype may be considered for vaccination." (PMID 35846349, 2022).
multiple sclerosis (1 paper, 2023). A progressive autoimmune disorder affecting the central nervous system resulting in demyelination. "In general, it can be concluded that increase of the expression of LASP1 and S100A6 genes and decrease the expression of the TUBA1C gene in multiple sclerosis disrupts NFAT transcriptional activity." (PMID 36970516, 2023).
nevus (1 paper, 2015). Nevus (or naevus, plural nevi or naevi, from nævus, Latin for "birthmark") is the medical term for sharply circumscribed[1] and chronic lesions of the skin or mucosa. "Benign melanocytic nevi show high LASP1 protein expression in MART1-positive nevus cells without nuclear LASP1 staining." (PMID 26061439, 2015).